BRCA2 (BRCA2 DNA repair associated)
Diseases named in the same sentence as BRCA2 in open-access papers (continued):
Sharing a sentence is not in itself a finding about the gene and the disease.
pancreatic cancer (continued). "Known gBRCA carrier individuals have a higher lifetime risk of developing pancreatic cancer compared to the normal population (with BRCA1: 2.2–3.0%; with BRCA2: 3.0–7.0%)." (PMID 38540206, 2024). "We explored various combinations of HDACi and PARPi +/− decitabine (hypomethylating agent) in pancreatic cancer cell lines BxPC-3 and PL45 (wild-type BRCA1 and BRCA2) and Capan-1 (mutated BRCA2)." (PMID 38829622, 2024). "BRCA1 and BRCA2 methylation was significant and correlated with decreased survival in patients with operable pancreatic cancer." (PMID 38577595, 2024). "We chose to work on BRCA2-associated pancreatic cancer, not only because BRCA2 mutation carriers have higher susceptibility to this disease, but also because we could leverage earlier work by Dave Tuveson and Tyler Jacks, in order to create a new model for familial pancreatic cancer in my lab." (PMID 39711301, 2024). "BRCA2 promoter methylation was also correlated in this group of patients with low-grade pancreatic cancer (p=0.018)." (PMID 38577595, 2024). "In addition to its important role in preventing cancer in patients and their close family members, identification of pathogenic or likely pathogenic variants, at least in BRAC1 and BRCA2, may inform therapeutic decisions in common cancers including breast, ovarian, prostate, and pancreatic cancers." (PMID 38730701, 2024). "To assess the potential impact of NLRP4 on the resistance of pancreatic cancer cells to olaparib, we administered varying doses of olaparib to NLRP4-knockdown or control stable BxPC-3 (BRCA wild type) and Capan-1 (possessing BRCA2 mutation) cell lines." (PMID 39187531, 2024). "Mutations in genes such as BRCA1, BRCA2, PALB2, and ATM are associated with an increased risk of pancreatic cancer, particularly in individuals with a family history of the disease." (PMID 39409171, 2024). "In the recent study we have tried to evaluate, for the first time, the prognostic value of BRCA1 and BRCA2 methylation in the cell-free DNA of pancreatic cancer patients." (PMID 38577595, 2024). "Another case was an Italian male diagnosed with pancreatic cancer at age 74 who harbored PSV in the BRCA2 and PMS2 genes." (PMID 39102164, 2024). "The risk of pancreatic cancer is 1–3% in patients with a BRCA1 mutation and 3–5% by the age of 70 years in patients with a BRCA2 mutation as compared to the general population with a risk of 0.5%." (PMID 39200847, 2024). "In familial pancreatic cancer (FPC), CDKN2A mutations, along with those in BRCA2 and PALB2, were prevalent, particularly in FPC probands, highlighting their significance in hereditary pancreatic cancer." (PMID 38666907, 2024). "The second most commonly mutated DDR gene after BRCA2 was ATM, with 5 mutated cases in the MSK-IMPACT pancreatic cancer cohort." (PMID 36975505, 2023). "Overall, these data support that, in addition to synthetic lethality between POLQ and BRCA2, cytosolic DNA damage products that accumulate in the presence of POLQ inhibition activate cGAS-STING signaling in BRCA2-deficient pancreatic cancer cells." (PMID 36976649, 2023). "Protein‐truncating variants in three DNA damage repair genes (PALB2, BRCA2, and ATM) were associated with a significant risk of pancreatic cancer (p < 0.05), with odds ratio ranging from 5.03 to 10.03." (PMID 36999792, 2023). "BRCA1 and BRCA2 (BRCA1/2) are the most frequently investigated genes among Caucasian pancreatic cancer patients, whereas limited reports are available among Asians." (PMID 37951914, 2023). "As discussed in a previous section, besides BRCA1 and BRCA2 mutations, mutations in PALB2, ATM, ATR, BRIP1, BARD1 and CDK12 are observed in low frequencies in pancreatic cancers." (PMID 36975505, 2023).
pancreatic cancer (continued). "PALB2, BRCA2, and ATM PGVs were associated with high risks for pancreatic cancer in the Chinese population." (PMID 36999792, 2023). "Patients with KRAS wild‐type disease and early‐onset pancreatic cancer (EOPC) harbored actionable mutations including BRAF, EGFR, ERBB2, and MAP2K1/2.PGVs in PALB2, BRCA2, and ATM were associated with high PDAC risk in the Chinese population." (PMID 36999792, 2023). "The prevalence of PVs in ATM among females with BC and pancreatic cancer was greater than the prevalence of BRCA2 PVs." (PMID 36856935, 2023). "For example, we did not include females with multiple PVs, and females with ATM or BRCA2 PVs who later developed pancreatic cancer, despite progress in earlier detection of pancreatic cancer." (PMID 36856935, 2023). "A recent study found that 7% of Canadian patients diagnosed with pancreatic cancer carry mutations in the BRCA1 and BRCA2 genes, with a higher prevalence observed in patients diagnosed at younger ages." (PMID 37232812, 2023). "Using this method, we examined CNVs in BRCA1 and BRCA2 in 293 Chinese patients with ovarian or pancreatic cancer." (PMID 38274092, 2023). "In contrast, the sensitivity of pancreatic cancers with somatic BRCA1 and BRCA2 mutations and with mutations in other homologous recombination (HR) repair genes to PARP inhibitors is less established and the subject of ongoing investigations." (PMID 36975505, 2023). "Rucaparib was evaluated in a phase II trial as a maintenance regimen for advanced pancreatic cancer (including both metastatic and locally advanced cases) in patients harboring BRCA1, BRCA2 or PALB2 germline or somatic mutations." (PMID 37366887, 2023). "P/LP variants of APC, BRCA2, BUB1B and ENG were identified in patients with pancreatic cancer, and MSH6 was identified in an NPaMC patient with both colorectal and esophageal cancers." (PMID 36896836, 2023). "Among total pancreatic cancer patients, ~10% of patients are categorized as familial pancreatic cancer (FPC) patients, carrying germline mutations of the genes involved in DNA repair pathways (e.g., BRCA2)." (PMID 37735513, 2023). "All three guidelines recommend pancreatic cancer screening in BRCA2, PALB2, ATM and Lynch syndrome patients with at least one affected FDR." (PMID 35884779, 2022). "This is a rare outcome, since the link between BC and pancreatic cancer has been reported for advanced-stage BC and related through rare BRCA1 and BRCA2 mutations." (PMID 36612726, 2022). "Studies have shown that in patients with pancreatic cancers with 2 or more FDR with pancreatic cancer, the prevalence of BRCA2 mutations ranges from 17% to 19%." (PMID 35626055, 2022). "The relative risk for pancreatic cancer in BRCA1 and BRCA2 mutant carriers is 2.3 and 3.5–10, respectively." (PMID 35163129, 2022). "The clinical importance of genetic testing of BRCA1 and BRCA2 in breast, ovarian, prostate, and pancreatic cancers is widely recognized." (PMID 35420638, 2022). "Similar to BRCA2, BRCA1 mutations also increase the risk of pancreatic cancer (relative risk, 2.26; 95% CI: 1.26–4.06)." (PMID 35884779, 2022). "A phase II study evaluated maintenance rucaparib in patients with platinum-responsive pancreatic cancer and a pathogenic germline and somatic variant in BRCA1, BRCA2, or PALB2." (PMID 35163129, 2022).
pancreatic cancer (continued). "In this review, we aim to describe the role of certain genes (BRCA1 and BRCA2) in the development of pancreatic cancer and the current and future research efforts underway to treat this subtype of disease." (PMID 35626055, 2022). "For example, pathogenic BRCA1, BRCA2 and PALB2 variants are associated with both male BC and pancreatic cancer." (PMID 36115878, 2022). "Tier I or II mutations related to hereditary cancer syndrome in pancreatic cancer were identified in BRCA1 (n = 2, 2.3%), BRCA2 (n = 2, 2.3%), PRSS1 (n = 1, 1.1%), MSH6 (n = 2, 2.3%), PMS2 (n = 1, 1.1%), and APC (n = 1, 1.1%)." (PMID 36463295, 2022). "In the case of pancreatic cancers, germline mutations occur in about 10–20% of patients, with mutations in BRCA1 and BRCA2 being the most common." (PMID 35626055, 2022). "A phase II, single-arm study evaluating the role of rucaparib as the maintenance therapy for advanced pancreatic cancer with the germline or somatic mutations in BRCA1, BRCA2, or PALB2 enrolled 46 patients, 42 of whom were eligible for the evaluation." (PMID 36556296, 2022). "The discovery of BReast CAncer gene 1 (BRCA1) and BRCA2 in the 1990s revolutionized the way we research and treat breast, ovarian, and pancreatic cancers." (PMID 35626055, 2022). "The lifetime risk of pancreatic cancer is about 1% for BRCA1 mutant carriers and 4.9% for BRCA2 mutant carriers." (PMID 35163129, 2022). "This phase 2 trial evaluates the efficacy of olaparib in 299 patients with advanced breast, ovarian, prostate, and pancreatic cancers harboring BRCA1 and/or BRCA2 mutations." (PMID 35328658, 2022). "The discovery of BRCA1 and BRCA2 in the 1990s revolutionized the way we research and treat breast, ovarian, and pancreatic cancers." (PMID 35626055, 2022). "We thus aimed to investigate the effect of combined treatment with PARP inhibitors and TRAIL receptor-stimulating agents in pancreatic cancer and its dependency on the BRCA2 gene status." (PMID 36358659, 2022). "Among unselected pancreatic cancer patient cohorts, multiple studies have shown to estimate the incidence of germline BRCA mutations ranged from 0.7–5.7% for BRCA2 and 0.3–2.3% for BRCA1." (PMID 34356066, 2021). "In a Danish proband with a history of breast and pancreatic cancer, a deletion affecting Exon 20 was found, altering the BRCA2 protein C-terminus." (PMID 33503928, 2021). "In a large cohort comprising 2,818 sporadic pancreatic cancers, our group identified gene mutations in BRCA1, BRCA2, or PALB2 in 1.3%, 3.1%, and 0.6%, respectively." (PMID 34707985, 2021). "Several studies reported that BRCA2 carriers had higher relative and cumulative risks of pancreatic cancer compared to BRCA1 carriers." (PMID 34356066, 2021). "Some pancreatic cancers with biallelic inactivation of the BRCA2 gene respond dramatically to poly (ADP-ribose) polymerase (PARP) inhibitors." (PMID 33555482, 2021). "Germline mutations associated with pancreatic cancer are ATM (2%–4%), BRCA1 (0%–1%), BRCA2 (8%–19%), CHEK2 (2%–9%), and PALB2 (3.1%–3.7%)." (PMID 33764904, 2021). "Independent of familial history, germline or somatic mutations in BRCA1 and BRCA2 genes occur in 5–10% of patients with pancreatic cancers, with a prevalence for BRCA2 ranging from 3.6–7% and <3% for BRCA1." (PMID 34200245, 2021).
pancreatic cancer (continued). "This surveillance is also recommended for individuals with three or more blood relatives with pancreatic cancer, and at least one of those affected FDR carrying the BRCA2 or PALB2 germline pathogenic variant." (PMID 34476650, 2021). "BRCA2 and ATM germline pathogenic variants are significantly more prevalent in familial pancreatic cancer patients." (PMID 34476650, 2021). "Resistance to PARPis was already proposed and demonstrated very early in the preclinical setting using a PARPi-resistant pancreatic cancer cell line with the intragenic deletion of c.6174delT of BRCA2." (PMID 33233320, 2020). "Retrospective studies suggest a survival benefit when platinum-based chemotherapy is administered to patients with pancreatic cancer harbouring a germline mutation in BRCA1, BRCA2 or PALB2 (mut-positive PDAC)." (PMID 31787751, 2020). "Breast cancer type 1 susceptibility protein (BRCA1) and Breast cancer type 2 susceptibility protein (BRCA2) mutations increase an individual’s risk of several cancer types, including pancreatic cancer." (PMID 33198737, 2020). "Identification of BRCA1 and BRCA2 mutations offers potential therapeutic advantages as they confer increased sensitivity to PARPi, reflecting a unique biology of BRCA-mutated pancreatic cancer cells." (PMID 33198203, 2020). "For example, BRCA1/BRCA2 testing criteria have broadened and now include additional indications such as personal history of pancreatic cancer and unaffected women with only minimal family history." (PMID 31853058, 2020). "Hereditary breast, ovarian, and pancreatic cancers are associated with the presence of germline pathogenic (P) or likely pathogenic (LP) variants in the BRCA1 and BRCA2 genes." (PMID 32957588, 2020). "In particular, two women presented a first-degree relative, nine women (one BRCA2 carrier) presented a second-degree relative and one patient had one third-degree relative with pancreatic cancer." (PMID 32429297, 2020). "In summary, a strong association between pancreatic cancer and BRCA1 and BRCA2 mutations is documented." (PMID 33198203, 2020). "The results of the phase III Pancreas Cancer Olaparib Ongoing (POLO) trial, which showed great promise for enrolled patients with metastatic pancreatic cancer with mutation in BRCA1 or BRCA2, who were previously treated with platinum-based chemotherapy." (PMID 32635552, 2020). "It was found that the family with BRCA1 mutant had pancreatic cancer, gastric cancer, cervical cancer and esophageal cancer, while the family with BRCA2 mutant had lung cancer, rectal cancer and close relatives of retroperitoneal tumor." (PMID 31775908, 2019). "Like BRCA1 (FANCS) and BRCA2 (FANCD1), monoallelic mutations in PALB2 confer familial susceptibility to breast, ovarian and pancreatic cancer, while biallelic PALB2 lesions cause Fanconi anemia (FA) subtype N (FANCN)." (PMID 31877165, 2019). "Capan‐1 cells showed significantly higher sensitivity to chlorambucil, as well as to cisplatin and olaparib, when compared to MIA PaCa‐2 pancreatic cancer cells with normal BRCA2 expression." (PMID 31273933, 2019). "The BRCA mutations, detected in our families with a history of pancreatic cancer, were more frequently located in the longest exon of each gene, EXON10 of the BRCA1 gene and in the EXON11 of the BRCA2 gene." (PMID 30736435, 2019). "An estimated 5~10% of pancreatic cancer is familial, with breast cancer susceptibility genes 1/2 (BRCA1/2) and partner and localizer of BRCA2 (PALB2) among established pancreatic susceptibility genes." (PMID 31877165, 2019). "We analyzed a homogenous set of BC patients excluding patients with breast and ovarian/pancreatic cancer duplicity and patients carrying mutations in non-BRCA1/BRCA2 BC-susceptibility genes." (PMID 31141992, 2019).
pancreatic cancer (continued). "In contrast to KPC animals (n = 28, T50 = 24.6 weeks), Palb2-KPC, Brca1-KPC or Brca2-KPC respectively developed PDAC with a much shorter pancreatic tumor-free median survival of 10.1, 11.9 and 13.7 weeks, respectively." (PMID 31877165, 2019). "We validated the effects of pimasertib on BRCA2 expression in an in vivo model by treating syngeneic pancreatic orthotopic xenografts derived from the KPC model of pancreatic cancer with pimasertib." (PMID 29545922, 2018). "There are no clear guidelines regarding screening of digestive cancers in BRCA2 carriers and even for pancreatic cancer screening (part of both the BRCA1 and BRCA2 phenotype) the recommendation is to include those carriers in prospective studies." (PMID 29456621, 2018). "Some studies also imply that Fanconi genes, in addition to BRCA2, play a role in inherited forms of pancreatic cancer." (PMID 29069866, 2017). "Mutations in the BRCA2 gene have been implicated in pancreatic cancer susceptibility, whereas the knockdown of LYN reduced human pancreatic cancer cell proliferation, migration, and invasion." (PMID 28347313, 2017). "A number of clinical studies were performed to estimate BRCA2 as potential prognostic and predictive biomarker for pancreatic cancer." (PMID 28452926, 2017). "Screening is recommended for high-risk individuals, including patients with a family history of pancreatic cancer or patients with an STK11, CDKN2A/p16, or a BRCA2 mutation with ≥1 affected first-degree relative." (PMID 28283772, 2017). "Larger studies are needed to further define the role of pancreatic cancer screening and the significance of abnormal imaging findings in BRCA1 and BRCA2 mutation carriers." (PMID 27069714, 2016). "Taken together these results suggest a possible regulation of BRCA2 mRNA by miR-19a and miR-19b that is dependent upon the cell type, with the greatest effect in pancreatic cancer cells." (PMID 27630665, 2016). "Two male relatives, one from a BRCA1 positive family and one from a BRCA2 positive family, were diagnosed with both breast and pancreatic cancer." (PMID 26236408, 2015). "unexpectedly reveal that BRCA2 heterozygosity promotes pancreatic cancer development in mice and men." (PMID 24268522, 2014). "The reported relative risk to develop pancreas cancer for BRCA1 mutation carriers is 2.26 and 3.55 for BRCA2 mutation carriers." (PMID 24959366, 2014). "Studies are ongoing to examine single-agent and combination PARPi therapy in BRCA2 mutant pancreatic cancers." (PMID 24616882, 2014). "The two BRCA genes are best known for their role in familial breast and ovarian cancers but BRCA2 also plays a role in pancreatic cancer development." (PMID 21512581, 2011). "Given the considerable use of the Capan-1 cell line as a model not only of BRCA2 dysfunction but also of pancreatic cancer, we used next generation sequencing technology to study the genomic sequence of this cell line." (PMID 21750719, 2011). "Increased drug sensitivity of pancreatic tumors obtained from BRCA2 carriers was described in several other case reports." (PMID 21819606, 2011). "Over expression of BRCA2 protein was shown to be lethal for the survival of human pancreatic cancer cell line Capan-1." (PMID 20202217, 2010). "The incidences of prostate and pancreatic cancer for BRCA1 and BRCA2 mutation carriers were obtained by multiplying the cohort and calendar period age-specific incidence rates from the general population." (PMID 18349832, 2008).